GANAB (glucosidase II alpha subunit)
Diseases named in the same sentence as GANAB in open-access papers (continued):
Sharing a sentence is not in itself a finding about the gene and the disease.
kidney disease (6 papers, 2020 to 2025). "She had a GANAB gene mutation, a gene tied to mild kidney disease but atypically developing rapidly progressing cysts (MIC 1E)." (PMID 40134995, 2025). "The diagnosis was confirmed with imaging and genetic testing, revealing a GANAB gene mutation - likely pathogenic, which typically presents with mild kidney disease." (PMID 40134995, 2025). "Furthermore, several VUS in known renal disease genes were analyzed by means of retrospective phenotyping or upon complementary DNA (cDNA)-based splice site analysis (GANAB: c.2319G>A, p.Ala773=, PARN: c.1405+3A>G in ID52.1, SEC63: c.1936–8->TTT in ID20.1 and ID97.1), disproving pathogenicity." (PMID 32398770, 2020). "In contrast to his father, however, he also showed an additional VUS in GANAB/PKD3 (c.602A>G, p.Asp201Gly, no entry in gnomAD/HGMD) potentially explaining the accelerated course of renal disease (ESRD-onset at 30 vs. ESRD-onset at 56 yrs)." (PMID 32398770, 2020).
tumor (6 papers, 2021 to 2025). "In addition to GANAB, there are numerous N-glycosylation-associated markers that were reported being strongly associated with tumor progression such as DPAGT1." (PMID 35879690, 2022). "In the correlation analysis of GANAB with the clinical factors, we found that GANAB was significantly correlated with tumor cell mitosis (Ki67 as a marker), with p-value of 0.0319." (PMID 35879690, 2022). "We confirmed global epigenetic modification associated with reduced H4R3me2S and re-expression of tumour suppressors, such as EIF3F, FOXP4, ZBTB4, GANAB, TMEM141, in association with loss of clonogenicity." (PMID 33795785, 2021). "The expression of GANAB, an indicator of poorer prognosis, was further validated to be increased with tumor grades, tumor stages, and luminal subtypes of UC, indicating that GANAB might be attributed to the pathogenesis of UC." (PMID 35879690, 2022). "Based on our results and literature rationales, the roles of GANAB in the proliferation and migration of UC tumor cells might be mediated by the aggregation of SGs during ER stress." (PMID 35879690, 2022). "Additionally, in 33.3% (12/36) MIBC cases, we found that the tumor cells at the invasive fronts of tumor margin exhibited much higher expression of GANAB than the tumor cells inside the tumor body, and more brown granules were observed at the invasive fronts." (PMID 35879690, 2022). "Notably, tumor cells at the invasive front of the tumor margin showed stronger GANAB expression than the tumor cells inside the tumor body in UCs." (PMID 35879690, 2022). "Interestingly, proteins inversely correlated with tumor size included GANAB and GALE." (PMID 41441336, 2025). "While all proteins, as expected, were correlated with tumor stage according to proteomic data, GANAB, THIC/ACAT2, SEPT8, PPIA, and GALE showed an inverse correlation with tumor size, whereas MYDGF displayed a positive correlation." (PMID 41441336, 2025). "Similar results were found for GANAB vs. GEMIN5, both of which are located within G3BP1 genomic loci and also driven by copy number alterations in tumor." (PMID 35879690, 2022). "In order to study the molecular mechanism of CALR involved in tumor progression, we used String and GeneMANIA databases finding that PDIA3, B2M, GANAB, CANX, and TAPBP interact with CALR." (PMID 34910788, 2021). "Furthermore, the abundance of proteins such as GANAB, GALE, THIC, SEPT8, and MYDGF/C19orf10 correlated with tumor size, suggesting their potential as prognostic biomarkers." (PMID 41441336, 2025). "Nonetheless, the dysregulation of the amount of both GANAB and GALE suggests that alterations in their expression may lead to aberrant glycosylation, thereby contributing to tumor progression in NMIBC." (PMID 41441336, 2025). "Overexpression of tumour suppressors, such as EIF3F, FOXP4, ZBTB4, GANAB, TMEM141 was observed." (PMID 33795785, 2021).
GANAB also shares sentences with these, for which no sentence is quoted: infection (2 papers); metastatic melanoma (2); multiple sclerosis (2); Renal cyst (2); adult respiratory distress syndrome (1); Brain atrophy (1); cervical cancer (1); ciliopathies (1); colon cancer (1); congenital anomalies of the kidney and urinary tract (1); COVID-19 (1); dilatation (1); infectious disease (1); large intestine cancer (1); liver cancer (1); liver disease (1); lymph node metastases (1); medullary cystic kidney diseases (1); metabolic disorders (1); nephronophthisis 1 (1); Nephropathy (1); neurological diseases (1); osteoarthritis (1); polycystic liver disease 1 (1); viral infections (1).